TSPO (translocator protein)
Diseases named in the same sentence as TSPO in open-access papers (continued):
Sharing a sentence is not in itself a finding about the gene and the disease.
tumor (continued). "Positron emission tomography (PET) imaging of the 18 kDa translocator protein (TSPO) is known as surrogate marker of activated microglia and macrophages and enables non-invasive assessment of the tumor microenvironment and peri-/intratumoral inflammation as well as TSPO-positive tumor cells." (PMID 42216973, 2026). "The TSPO targeting ligand 18F-DPA-714 PET was utilized to detect M2-polarized TAMs in a triple-negative breast cancer tumor model (TNBC) with the aim of providing insights into tumor stratification and prognosis evaluation." (PMID 40725764, 2025). "Furthermore, GPX4 is elevated in malignant tumors compared to benign specimens and is negatively correlated with TSPO expression in tumor specimens." (PMID 40842566, 2025). "In addition, TSPO gene expression was significantly higher in tumor tissues compared to non‐tumor tissues, with expression levels increasing with tumor grade and varying significantly across cancer stages." (PMID 40550494, 2025). "This reinforces our observation of increased TSPO expression correlating with tumor aggressiveness." (PMID 40550494, 2025). "However, more research is needed to understand TSPO's role in tumor biology and develop targeted therapies." (PMID 40550494, 2025). "Stage 0 tumors had mean TSPO expressions of 19.42 in tumor tissues and 16.26 in non‐tumor tissues." (PMID 40550494, 2025). "We used these indices to evaluate the relationship between TSPO expression and tumor cell stemness." (PMID 40936684, 2025). "IHC staining also confirmed that TSPO was expressed at low levels in malignant tumor samples." (PMID 40842566, 2025). "Nevertheless, future studies utilizing patient-derived models or engineered systems with high TSPO expression are warranted to determine whether TSPO depletion might enhance tumor growth or stemness." (PMID 40936684, 2025). "Furthermore, GPX4 is elevated in malignant tumors compared to benign specimens and negatively correlated with TSPO expression in clinical tumor specimens." (PMID 40842566, 2025). "Notably, in this study, we found that TSPO gene expression levels increased with tumor grade in both CRC tumors and adjacent healthy tissue samples, whereas they decreased with advancing cancer stage." (PMID 40550494, 2025). "TSPO and COX4I1 are mitochondrial-associated proteins that participate in metabolic processes and oxidative phosphorylation, potentially contributing to the reprogramming of tumor energy metabolism." (PMID 40936684, 2025). "A positive but statistically nonsignificant (P > .05) correlation was also observed between global whole-brain (GM & WM) and cortical [11C](R)PK11195 DVR (GM) with tumor volume and % annual tumor growth rate, with larger faster-growing tumors trending to greater brain TSPO expression." (PMID 38962752, 2024). "The presence of TSPO also correlated with the level of cholesterol inside the tumor cells." (PMID 38585455, 2024). "In this regard, weakest correlation was observed between contralateral TSPO expression and tumor volumes in FET-PET, which may be due to the limited sample size." (PMID 39150564, 2024). "Contralateral TSPO was associated with persisting epileptic seizures and shorter overall survival independent of the tumor phenotype." (PMID 39150564, 2024). "They found that TSPO tracer uptake significantly correlated with tumor grade at recurrence and that a median maximum standardized uptake value < 1.68 predicted significantly longer median post-recurrence survival (41.6 vs. 12.6 months) and median time to treatment failure (14.9 vs. 6.2 months)." (PMID 38730666, 2024). "We note that human TSPO-PET signal changes in tissue distant of the tumor could still be influenced by infiltrating tumor cells, which even exceeded the cellular uptake of the same TSPO tracer compared to myeloid cells." (PMID 39150564, 2024).
tumor (continued). "The combinatorial settings of TSPO-wildtype/knock-out host mice transplanted with TSPO-wildtype/knock-out tumor cells could help to better understand the contribution to the TSPO signal." (PMID 38255293, 2024). "In addition to the identification of immune cells as the underlying source of distant TSPO-PET signal increases, we found a spatial dependency of contralateral neuroinflammation from the primary tumor site." (PMID 39150564, 2024). "The superior performance of TSPO PET might be attributed to the fact that TSPO expression is correlated with tumor aggressiveness." (PMID 38396261, 2024). "Furthermore, we describe a positive correlation of contralateral TSPO-PET signals not only with tumor volumes in PET and MRI but also with TSPO expression of the tumor." (PMID 39150564, 2024). "Notably, TSPO inhibitor PK11195 combines with anti‐PD‐1 antibody showing a synergistic anti‐tumor effect in a mouse model." (PMID 36994647, 2023). "Our data indicate that targeting TSPO may be able to sensitize GB to immune cell-mediated cytotoxicity by circumventing tumor intrinsic TRAIL-resistance." (PMID 37158962, 2023). "Similarly, low TSPO levels were associated with worse DSS (p = 0.013 in stage 0–II and p = 0.042 in stage III–IV) in all tumor stages." (PMID 38162485, 2023). "The mitochondrial TSPO is located on the outer mitochondrial membrane and its expression is increased in various tumors compared with normal tissues, suggesting that TSPO is a promising tumor‐specific target." (PMID 36994647, 2023). "Therefore, in the future, TSPO would be exploited as a therapeutic target for HG likely to recur from residual tumor cells." (PMID 36831378, 2023). "Several PET-derived parameters were calculated (SUV and TBRmax), and tumor volumes of TSPO-positive lesions were measured by applying various SUV-based thresholds (SUVBG × 1.6, SUVBG × 1.8, SUVBG × 2.0), thus generating corresponding volumes V1.6, V1.8, and V2.0." (PMID 37238297, 2023). "Both TSPO mRNA and TSPO protein expression were higher in healthy corresponding tissue compared to tumor (p < 0.001), showing significantly lower TSPO expression in tumors originating from the oral cavity (p = 0.001), larynx (p = 0.002), tonsils (p = 0.031), and tongue (p < 0.001)." (PMID 38162485, 2023). "We validated TSPO-mediated protection against cytotoxic molecules in the T cell supernatants by cytotoxicity assays, where TSPO-deficient BTIC13 clones and BTIC129 cells exerted increased apoptosis upon treatment with activated supernatant compared to TSPO-proficient tumor cells." (PMID 37158962, 2023). "Our data thereby provide an indication that therapeutic targeting of TSPO may be a suitable approach to sensitize GB to immune cell-mediated cytotoxicity by circumventing tumor intrinsic TRAIL resistance." (PMID 37158962, 2023). "TSPO expression was also analyzed in different primary tumor subsites and according to p16 status." (PMID 38162485, 2023). "The TSPO expression was 16-fold higher in the tumor than the normal brain tissues." (PMID 36831378, 2023). "The authors indicated that the TSPO PET volume increase under CSF-1R inhibition-induced GAMs depletion might result from the increase in TSPO+ tumor cell proliferation, as indicated by the simultaneously increased in [18F]FET PET volume." (PMID 35804911, 2022). "Interestingly, we observed an influx of apparently round CSF-1R+, TSPO+ cells within the tumor area." (PMID 35115369, 2022). "The TSPO is located in the mitochondrial membrane and is overexpressed in activated glial cells in neuroinflammation models and in different tumor cell lines, participating in the modulation of cell proliferation and tumorigenesis." (PMID 36559209, 2022). "This may be due in part to the use of a uniform tumor VOI, which in principle includes an excessive amount of non-tumor tissue in the case of small tumors, but also in part to the role of various origins of the TSPO signal, as discussed in more detail below." (PMID 35453488, 2022).
tumor (continued). "The extent of TSPO expression in immunohistochemistry was visually congruent with the extent of [18F]GE-180 uptake in autoradiography as well as with the tumor borders in H&E staining with an accentuated [18F]GE-180 uptake and TSPO expression at the tumor margin." (PMID 35453488, 2022). "Moreover, the cerebellum which is frequently used as a reference region because of its low basal expression of TSPO was infiltrated by the tumor in our PDOX DIPG model." (PMID 36293329, 2022). "They found that in TSPO+/+ the signal extended beyond the tumor, whereas in TSPO KO the signal was lower and restricted to the tumor, indicating that in the wildtype situation—as in our study—the TSPO PET signal in the GL261 model is indeed of diverse cellular origin." (PMID 35453488, 2022). "However, the delineation of the tumor remains challenging due to the heterogeneous expression of TSPO." (PMID 36293329, 2022). "Therefore, current research should be supported by in-depth characterization in preclinical glioma models as a back-translation approach or by the combination of different biological markers to characterize the aggressive tumor mass and TSPO." (PMID 35804911, 2022). "Other roles indicated for TSPO include porphyrin transport, cellular responses to stress, inflammation, and tumor progression." (PMID 35444539, 2022). "Interestingly, the number of (Iba-1+) microglia/macrophages increased with tumor grade while only a few cells expressed TSPO." (PMID 35804911, 2022). "Moreover, several reports found a positive correlation between tumor grade and TSPO expression, with the highest expression observed in GBM." (PMID 34572751, 2021). "As TSPO is considered to be an inflammatory macrophage marker, we also determined the proportion of monocytes, migratory monocytes/macrophages and macrophages with different polarisation stages (M1 and M2) in the tumours." (PMID 33340054, 2021). "Although not specifically targeting TAMs, Wu and colleagues carried out a study in 2014 in which they used N, N-Diethyl-2-(2-(4-(2-[18F] fluoroethoxy) phenyl)-5, 7-dimethylpyrazolo [1, 5-a] pyrimidin-3-yl) acetamide ([18F]-DPA-714), a tracer targeting TSPO, to differentiate inflammation from tumor." (PMID 33923410, 2021). "The higher tumor volumes in the DMSO-treated animals may suggest higher TSPO levels in the right hemisphere of these mice, compared to the TMZ-treated group, because tumor cells express TSPO as well." (PMID 33500706, 2021). "Indeed, TSPO is expressed on the outer mitochondrial membrane of activated microglia/macrophages, tumor cells, astrocytes and endothelial cells." (PMID 34012924, 2021). "One explanation could be a de-masking effect of peri-tumoral TSPO expression sources stemming from tumor shrinkage." (PMID 33500706, 2021). "In principle, TSPO could be involved in the M1, anti-tumor/pro-inflammatory, or M2, pro-tumor/anti-inflammatory, response." (PMID 33066460, 2020). "Importantly, TSPO tumour signal was already detectable at pre-symptomatic stages, i.e. in still healthy appearing animals." (PMID 32561881, 2020). "Interestingly, TSPO-PET not only visualizes the tumor mass but also activated microglia in TAM and potentially additional inflamed components of GBM." (PMID 33066460, 2020). "Although second and third generation TSPO radioligands with higher specific binding have since been developed, TSPO imaging in GBM has major limitations including tumor heterogeneity and inability to distinguish signal caused by radiation therapy from signal due to the tumor microenvironment." (PMID 32012954, 2020). "In the tumor, border dispersed cells strongly positive for TSPO were visible (arrows in the tumor border), likely showing invading cells and macrophages, while in the tumor-free regions, these expression patterns were weaker (arrows in tumor-free areas)." (PMID 31963507, 2020).
tumor (continued). "However, not only tumor cells express TSPO; microglia/macrophages, endothelial cells, and pericytes were also strongly positive for TSPO in the tumor regions of our GBM models." (PMID 31963507, 2020). "A combination of TSPO-PET and FET-PET could be a promising way to visualize tumor-associated myeloid cells and select patients for treatment strategies targeting the myeloid compartment." (PMID 31963507, 2020). "In addition to GBM, other tumor types including stomach, lung, hepato-carcinoma (liver), kidney, and breast, also overexpress TSPO (10- to 20-fold) relative to the levels in healthy tissue." (PMID 31661894, 2019). "Motivated by our previous results that TSPO radiotracers can sensitively detect TSPO expression in LPS-induced neuroinflammation and tumor models, we further investigated the translation of these findings to other in vivo model related with abnormal TSPO expression." (PMID 29342117, 2018). "Beyond its relevance to neuropharmacology, TSPO has been reported to be overexpressed in some forms of cancer, and expression of TSPO has been shown to correlate to the aggressiveness of the tumour." (PMID 29897975, 2018). "Furthermore, it was demonstrated that selectively increasing TSPO expression in tumor cells by low-level light treatment facilitated ALA-PDT-induced tumor cell death." (PMID 29746502, 2018). "In these studies, the authors showed that [18F] VUIIS1008 exhibited a rapid uptake in TSPO-rich tissues and suggested that this radiotracer might improve tumor detection, particularly for those tumors expressing modest levels of TSPO." (PMID 29177913, 2017). "In vitro studies on TSPO-rich tumor cells suggest that radiolabeled 1 may have potential to act as a useful SPECT radiotracer for the evaluation of TSPO-overexpressing tissues, and provides the foundation for further in vivo biological evaluation." (PMID 27399688, 2016). "This hypothesis is supported by previously published results which demonstrated minimal level of [18F]DPA-714 binding ex vivo in mouse muscle tissue compared to high TSPO-expressing tumor tissues." (PMID 26194010, 2016). "Immunoblotting of crude tumor lysates yielded similar results: higher levels of the microglia/macrophage marker F4/80 were present in Nrp1MgKO tumor lysates, accompanied by increased expression of TSPO, a marker of neuro-inflammation." (PMID 26755653, 2016). "The development of nanoparticles and vehicles that could exploit TSPO to increase the bioavailability and selective delivery of radiosensitizers into tumour tissue and enhance the effect of conventional fractionated radiation seems promising." (PMID 27077069, 2016). "In addition, the evidence of elevated TSPO in neoplastic cells has led to studies investigating TSPO as a transporter of anticancer drugs for brain delivery and a selective target for tumour tissue." (PMID 27077069, 2016). "Finally, the VOIs of increased 123I-CLINDE at baseline appeared to be a good predictor of tumour progression, suggesting a potential for TSPO imaging to provide clinically relevant information regarding areas of proliferation." (PMID 27077069, 2016). "There is now evidence that TSPO expression might serve as a biomarker of tumor progression, metastatic potential, and overall prognosis in several human tumors." (PMID 25853015, 2015). "In tumor cells, TSPO appeared to be confined to the cytoplasm and occasionally the nucleus." (PMID 26517124, 2015). "Western blotting was performed to verify TSPO production by the tumor." (PMID 25853015, 2015). "Recently, TSPO has attracted attention as a possible molecular target for tumor imaging and chemotherapy, and initial clinical trials have indicated that TSPO ligands might be valuable in the treatment of neurological and psychiatric disorders." (PMID 25477872, 2014).
tumor (continued). "Notably, many tumor seed localizations showed strongest correlation with contralateral regions of the frontal and temporal lobe, raising the question of effects of this particular regional involvement in higher TSPO expression on patient symptoms." (PMID 39150564, 2024). "Since an increased amount of tumor-infiltrating immunosuppressive cells (i.e., GAMs) were found to correlate with a more intense TSPO signal, this imaging modality might be applied to select patients suitable for GAMs-targeted immunotherapies, currently under investigation." (PMID 37238297, 2023). "Notably, TSPO expression in tumor cells positively correlated with tumor grade." (PMID 37238297, 2023). "Therefore, we restricted our functional assays to TSPO knockdown tumor cells." (PMID 37158962, 2023). "However, tumor cells also express TSPO, and the volumetric analysis showed increased 18F-DPA-714 PET volumes on day 14 at the same level as in the nontreated group because of glioma progression, which may hide possible immunologically induced changes." (PMID 35115369, 2022). "Furthermore, follow-up change in gadolinium-CE VOI overlapped to a greater extent with baseline [123I]CLINDE VOI than [18F]FET VOI, indicating that TSPO SPECT could be more representative of progressive tumor areas than [18F]FET." (PMID 35804911, 2022). "Moreover, TSPO expression was proven in several brain structures apart from the GL261 tumor such as CA1-CA3 neurons and dentate gyrus in hippocampus, ependyma, cerebellar Purkinje cells, and glial scar of the inoculation process, which also mirrors PET and autoradiography findings in sham mice." (PMID 35453488, 2022). "Moreover, in the CX3CR1-GFP mouse, we found that microglia within the tumor expressed TSPO." (PMID 31963507, 2020). "In addition, in the murine GBM models, evenly dispersed TSPO-positive cells could be observed in tumor border and tumor-free areas (arrows)." (PMID 31963507, 2020). "Therefore, the question to which extent TSPO might contribute to one phenotype or another and, accordingly, to the pro-inflammatory/anti-tumor or anti-inflammatory/pro-tumor responses cannot be answered yet." (PMID 33066460, 2020). "Hence, selective TSPO ligands may be able to target drug delivery systems for the therapy of diseases overexpressing TSPO, such as tumours." (PMID 29641449, 2018). "The supposed role of TSPO in maintaining and reestablishing cell homoeostasis following oxidative stress could also be exploited in TSPO-positive tumours to increase radio and/or chemosensitivity to compounds that are routinely used in the treatment of patients with CNS cancer." (PMID 27077069, 2016). "Finally, immunohistochemical analysis shows TSPO-immunoreactivity in most of the tumor cells." (PMID 25853015, 2015). "Overexpression of TSPO in CRC cells enhances proliferation and tumor marker expression (CEA and CA19‐9) while inhibiting apoptosis, whereas TSPO interference results in reduced proliferation and increased apoptosis." (PMID 40550494, 2025). "The current study aimed to assess the levels of the TSPO gene expression in both tumor and non‐tumor tissue samples obtained from patients with CRC, considering variables including gender, age, tumor grades, and cancer stages." (PMID 40550494, 2025). "The mean of Translocator Protein (TSPO) gene expression in colorectal cancer tumor and non‐tumor tissue samples." (PMID 40550494, 2025). "We correlated mean TSPO-PET signal intensities of the contralateral hemisphere with maximum and mean PET signal intensities of the tumor and found a significant correlation for both comparisons." (PMID 39150564, 2024).